TBC1D19 (TBC1 domain family member 19)
Description:
May act as a GTPase-activating protein for Rab family protein(s).
Synonyms: FLJ11082
Tractability: PROTAC: ubiquitination databases record sites on it; its protein half-life has been measured.
Gene: Protein-coding gene on chromosome 4 (26,576,437 to 26,756,223, forward strand). Ensembl gene ENSG00000109680.
Subcellular location (Human Protein Atlas): Nuclear membrane; Nucleoplasm
Gene Ontology:
Molecular function: protein binding
Biological process: regulation of cilium assembly
Genetic constraint (gnomAD): Loss-of-function variants: 10 observed, 25.43 expected, observed/expected ratio (o/e) 0.39, 90% interval 0.24 to 0.67. The upper end of that interval is the gene's LOEUF score, 0.67, which puts it in group 2 of 6, group 1 being the genes least tolerant of losing a copy. Missense variants: 168 observed, 241.51 expected, observed/expected ratio (o/e) 0.7, 90% interval 0.61 to 0.79. Synonymous variants: 96 observed, 90.61 expected, observed/expected ratio (o/e) 1.06, 90% interval 0.9 to 1.25.
Homologues: Orthologues: chimpanzee TBC1D19 (99% identical), macaque TBC1D19 (99% identical), dog TBC1D19 (98% identical), pig TBC1D19 (98% identical), rat Tbc1d19 (98% identical), mouse Tbc1d19 (97% identical), rabbit TBC1D19 (96% identical), guinea pig TBC1D19 (88% identical), tropical clawed frog tbc1d19 (85% identical), zebrafish tbc1d19 (77% identical), Drosophila melanogaster CG7742 (38% identical).
Diseases named in the same sentence as TBC1D19 in open-access papers:
TBC1D19 is named in the same sentence as 6 diseases in open-access papers, as found by Europe PMC text mining. Sharing a sentence is not in itself a finding about the gene and the disease. The quoted sentences say what the papers report.
melanoma (2 papers, 2020 to 2022). A malignant, usually aggressive tumor composed of atypical, neoplastic melanocytes. "Seven prognosis associated TBCs genes including TBC1D13, TBC1D16, TBC1D7, TBC1D10C, TBC1D19, TBC1D8B, and TBC1D15 were identified in melanoma." (PMID 33194704, 2020). "Protein expression of TBC1D10C, TBC1D19, TBC1D16, and TBC1D13 were increased significantly in melanoma tissues." (PMID 33194704, 2020).
gastric cancer (1 paper, 2023). A primary or metastatic malignant neoplasm involving the stomach. "By qRT-PCR to detect RNA after RNase R treatment, we found that hsa_circ_0069382 tolerated the digestion by RNase R in GES-1 and gastric cancer cells, whereas its homologous linear molecule TBC1D19 was digested." (PMID 36841760, 2023).
neurodegenerative disease (1 paper, 2023). A disorder of the central nervous system characterized by gradual and progressive loss of neural tissue and neurologic function. "The Tbc1d19 gene is predicted to act as a GTPase-activating protein (GAP) for Rab proteins and is relatively uncharacterised in neurodegenerative diseases or TBI." (PMID 37464280, 2023).
TBC1D19 also shares sentences with these, for which no sentence is quoted: schizophrenia (1 paper); skin cutaneous melanoma (1); tumor (1).